Y_RNA (Y RNA )
Gene: Miscellaneous RNA gene on chromosome 12 (48,809,911 to 48,810,016, forward strand). Ensembl gene ENSG00000207467.
Homologues: Orthologues: chimpanzee Y_RNA (100% identical), macaque Y_RNA (89% identical). Paralogues in human: RNY1P5 (83% identical), Y_RNA (83% identical), Y_RNA (81% identical), Y_RNA (79% identical), Y_RNA (78% identical), Y_RNA (76% identical), Y_RNA (75% identical), Y_RNA (74% identical), Y_RNA (73% identical), RNY1 (72% identical), Y_RNA (72% identical), RNY1P1 (71% identical), and 91 more.